ABCB5 (ATP binding cassette subfamily B member 5)
Diseases named in the same sentence as ABCB5 in open-access papers (continued):
Sharing a sentence is not in itself a finding about the gene and the disease.
gastric cancer (2 papers, 2022 to 2025). A primary or metastatic malignant neoplasm involving the stomach. "Recently, two preclinical studies demonstrated the mechanisms by which IL8 mediates platinum resistance by transactivating ATP-binding cassette transporters, i.e., ABCB1 in gastric cancer cells and ABCB5 in tumor-initiating cells of malignant pleural mesothelioma." (PMID 35264742, 2022). "In the training cohort, a prognostic model for gastric cancer was developed using univariate and multivariate Cox regression analyses, along with stepwise regression, incorporating the genes SNCG, MNAT3, DDO, ITGAD, FGF8, and ABCB5." (PMID 41323282, 2025).
glioma (2 papers, 2020). A benign or malignant brain and spinal cord tumor that arises from glial cells (astrocytes, oligodendrocytes, ependymal cells). "High levels of ABCB5 were associated with poor survival outcomes in HCC and in diverse cancer types including low‐grade glioma, colon adenocarcinoma, prostate adenocarcinoma and stomach adenocarcinoma as shown in TCGA data sets." (PMID 32783366, 2020). "In TCGA datasets, low‐grade glioma (LGG), colon adenocarcinoma (COAD), prostate adenocarcinoma (PRAD) and stomach adenocarcinoma (STAD) all demonstrated that elevated ABCB5 levels were significantly associated with poor overall survival." (PMID 32783366, 2020).
mesothelioma (2 papers, 2024 to 2025). A usually malignant and aggressive neoplasm of the mesothelium which is often associated with exposure to asbestos. "In mesothelioma stem cells, activation of ABCB5 has been identified as a key mediator of cisplatin resistance." (PMID 41573644, 2025). "Autocrine signaling loops, such as the Wnt/IL-1β/IL-8 pathway, can induce ABCB5 expression in mesothelioma stem cells." (PMID 41573644, 2025).
non-small cell lung carcinoma (2 papers, 2023 to 2025). A group of at least three distinct histological types of lung cancer, including non-small cell squamous cell carcinoma, adenocarcinoma, and large cell carcinoma. "CSCs of non-small cell lung cancer (NSCLC), Merkel cell carcinoma, and colorectal cancer (CRC) showed high expression of ABCB5." (PMID 40746888, 2025).
osteosarcoma (2 papers, 2021 to 2024). A usually aggressive malignant bone-forming mesenchymal neoplasm, predominantly affecting adolescents and young adults. "This article addresses the study of osteopontin (OPN), WNT3A, and ABCB5 as biomarkers in osteosarcoma (OS) patients." (PMID 39239573, 2024).
pancreatic carcinoma (2 papers, 2020 to 2025). "The study found that lower levels of miR-4282 were correlated with higher ABCB5 expression, advanced metastasis, and worse survival in patients with pancreatic cancer." (PMID 40445912, 2025). "Another study by Li and Hou demonstrated that ABCB5 plays an important role in the progression of pancreatic cancer." (PMID 40445912, 2025). "Specifically, their research highlighted that microRNA-4282 (miR-4282) limits the metastatic potential of pancreatic cancer cells by reducing ABCB5 expression." (PMID 40445912, 2025).
polycystic kidney disease (2 papers, 2022 to 2023). A usually autosomal dominant and less frequently autosomal recessive genetic disorder characterized by the presence of numerous cysts in the kidneys leading to end-stage renal failure. "Since it was shown that ABCB5+ MSCs had a similar renoprotective effect compared to adipose-derived stromal cells (ASCs) in a polycystic kidney disease (PKD/MHN) model, we included ASCs in our in vitro study for comparison." (PMID 38274791, 2023). "In preclinical studies, ABCB5+ MSCs have also shown to reverse metabolic reprogramming in polycystic kidney cells, suggesting a capacity for this cell subset to improve also organ function in kidney diseases." (PMID 38274791, 2023). "Preclinical, ABCB5+ MSCs were able to reverse metabolic reprogramming in polycystic kidney cells." (PMID 38274791, 2023). "The ABCB5+ MSCs have been studied in polycystic kidney disease (PKD), a group of inherited nephropathies characterized by the formation of multiple fluid-filled cysts in the kidney, which distorts the renal architecture and severely impairs filtration function." (PMID 36613507, 2022). "Another potential indication relates to the ability of ABCB5+ MSCs to reverse metabolic reprogramming in polycystic kidney cells, which might qualify ABCB5+ MSCs as a potential candidate for improving kidney function in diseased kidney." (PMID 36613507, 2022).
recessive dystrophic epidermolysis bullosa (2 papers, 2022 to 2023). "Human dermal MSCs expressing ATP-Binding Cassette member B5 (ABCB5) have shown therapeutic efficacy in clinical trials in chronic skin wounds or recessive dystrophic epidermolysis bullosa." (PMID 38274791, 2023). "ABCB5+ MSCs have already demonstrated therapeutic efficacy in clinical trials in chronic skin wounds and in recessive dystrophic epidermolysis bullosa." (PMID 38274791, 2023). "A range of preclinical studies has suggested therapeutic efficacy of ABCB5+ MSCs in a variety of currently uncurable skin and non-skin inflammatory diseases, which has been substantiated thus far by distinct clinical trials in chronic skin wounds or recessive dystrophic epidermolysis bullosa." (PMID 36613507, 2022).
Allergy (1 paper, 2023). An allergy is an immune response or reaction to substances that are usually not harmful. "The ABCB5-positive fraction also has an upregulation of Histamine Receptor 1 (HRH1), which regulates allergic responses in nasal and corneal epithelial cells, while non-competitive histamine antagonist (H1-receptor) is proposed for the treatment of allergy affecting the ocular surface." (PMID 37443766, 2023).
attention deficit-hyperactivity disorder (1 paper, 2024). A disorder characterized by a marked pattern of inattention and/or hyperactivity-impulsivity that is inconsistent with developmental level and clearly interferes with functioning in at least two settings (e.g. at home and at school). "Whole blood RNA from American adolescents with attention-deficit hyperactivity disorder showed a 1.9-fold increase in ABCB5 mRNA." (PMID 39267923, 2024).
Blindness (1 paper, 2023). Blindness is the condition of lacking visual perception defined as a profound reduction in visual perception. "ABCB5+ cells can regenerate a cornea in a mouse with limbal stem cell deficiency (disease of the corneal limbus causing blindness), suggesting a therapeutic potential of this cell population for treating some types of blindness." (PMID 38203368, 2023).
choriocarcinoma (1 paper, 2016). An aggressive malignant tumor arising from trophoblastic cells. "There is less data on the expression of the ABC family proteins in choriocarcinoma and placental site trophoblast tumours, however the limited data indicates that the majority of cases of choriocarcinoma or PSTT do not express ABCB5." (PMID 27871274, 2016).
corneal dystrophy (1 paper, 2019). The term corneal dystrophy embraces a heterogeneous group of bilateral genetically determined non-inflammatory corneal diseases that are usually restricted to the cornea. "Collectively, our results suggest that CRISPR/Cas9 genome editing targeting the TGFBI gene in human ABCG2+/ABCB5+ double-positive LESCs may be applied therapeutically in corneal dystrophy patients." (PMID 30753226, 2019). "Based on these data, knock out of mutant TGFBIp in ABCG2+/ABCB5+ LESC from corneal dystrophy patients may be treatment strategy for corneal dystrophy patients." (PMID 30753226, 2019).
diabetes (1 paper, 2022). "Moreover, diabetes, at least in mice, is associated with reduced numbers of ABCB5+ MSCs along with profound changes in the dermal stromal niche." (PMID 36613507, 2022). "Angiogenesis), it is likely that a reduction in or the dysfunction of dermal ABCB5+ MSCs contribute to reduced angiogenesis and wound healing observed in diabetes." (PMID 36613507, 2022).
EEC syndrome (1 paper, 2023). EEC syndrome is a genetic developmental disorder characterized by ectrodactyly, ectodermal dysplasia, and orofacial clefts (cleft lip/palate). "The use of GMP-compliant ABCB5+ cells might be a new strategy for the treatment of bilateral LSCD, as in the EEC syndrome, which requires allogeneic LSC transplantation." (PMID 36766837, 2023).
ischemia (1 paper, 2023). A hypoperfusion of the BLOOD through an organ or tissue caused by a PATHOLOGIC CONSTRICTION or obstruction of its BLOOD VESSELS, or an absence of BLOOD CIRCULATION. "More experiments needed be planned to establish the direct relationship between ABCB5+ MSCs, Ca2+ homeostasis, and protection from ischemia injury in the future." (PMID 36759868, 2023). "This provides new evidence of a protective effect of ABCB5+ MSCs in ischemia and supports the application of ABCB5+ MSCs for novel therapeutic approaches in the future." (PMID 36759868, 2023). "In acute-on-chronic ischemia, ABCB5+ MSCs treated mice showed a higher microvascular density, increased SERCA2a expression and PLN phosphorylation relative to untreated controls." (PMID 36759868, 2023).
kidney cancer (1 paper, 2023). Primary or metastatic malignant neoplasm involving the kidney. "ABCB5 was found to have been decreased in both cell lines, as it strongly regulates a drug efflux that confers chemoresistance to human kidney cancer cells." (PMID 37764501, 2023).
liver fibrosis (1 paper, 2021). "Umbilical-cord-derived MSCs and also allogenic ABCB5-positive MSCs that improve liver fibrosis enhance regeneration, suppress inflammation, and downregulate Notch and Stat1/Stat3 signaling in rats are under clinical trials (NCT04822922, NCT03860155) for the treatment of patients with ACLF." (PMID 34820395, 2021).
Merkel cell carcinoma (1 paper, 2024). "Blockade of ABCB5 with an anti-ABCB5 mAb reduced cancer growth in a Merkel cell carcinoma xenograft." (PMID 39267923, 2024).
nephrotoxicity (1 paper, 2023). Toxicity that causes injury to the kidney or damages its function. "Having shown that clinical-grade human ABCB5+ MSCs/their secreted naïve CM elicit both pro-regenerative and immunomodulatory effects in the xenotransplant context, we tested their therapeutic potential on a cisplatin-induced nephrotoxicity model in immunocompetent SD rats." (PMID 38274791, 2023).
ocular tumor (1 paper, 2021). "Together, these findings confirm the ocular tumor susceptibility of the animal model used, which, in turn, counts against a tumor risk of treatment with ABCB5+ LSCs." (PMID 33741066, 2021).
sarcoma (1 paper, 2019). A usually aggressive malignant neoplasm of the soft tissue or bone. "Based on these genetic association data we propose that ABCB5 and C16orf96 are novel candidate risk genes for sarcoma." (PMID 31053105, 2019). "The ABCB5 gene was found to have a higher burden of putative regulatory variants (OR = 4.9, p-value = 0.007, q-value = 0.04) based on allele counts in sarcoma cases compared to controls." (PMID 31053105, 2019).
T-cell lymphomas (1 paper, 2015). "It was found that there were significant differences in ABC-transporter expression between B- and T-cell lymphomas, with T-cell lymphomas showing a higher ABCB5 and ABCC5, and lower ABCC1 expression compared to B-cell lymphomas." (PMID 29061939, 2015).
venous ulcers (1 paper, 2022). "For the first clinical trial of ABCB5+ MSCs, the cells were derived from small skin biopsies of the patients and expanded ex vivo, before being topically applied onto chronic, standard therapy-refractory venous ulcers (CVUs)." (PMID 36613507, 2022).
tumor (83 papers, 2006 to 2026). "Elevated expression of ABCB5 was associated with tumor growth, aggressiveness, multidrug resistance, cancer stemness, and poor overall survival in cancers." (PMID 40746888, 2025). "Other studies have shown that ABCB5 expression, by immunochemistry, is associated with tumor thickness, a prognostic factor for patient survival." (PMID 39267923, 2024). "Being highly expressed in LCSCs, ABCB5 is associated with tumor progression, chemoresistance, and recurrence in patients with HCC70." (PMID 34031441, 2021). "Accordingly, TRP2 and ABCB5 expression was significantly associated with lower tumor thickness of the primary (p = 0.013 and p = 0.025)." (PMID 33805080, 2021). "The expression of ABCB5 was also significantly associated with tumor progression and recurrence, acting as an energy-dependent drug efflux transporter and function during the multidrug resistance process." (PMID 25313648, 2014). "Research has indicated that ABCB5 was associated with tumor cell migration and invasion." (PMID 40746888, 2025). "ABCB5 expression was reported to be associated with larger tumor size in PTC." (PMID 35837087, 2022). "So far, ABCB5 has mostly been described in cancer, where it was associated with tumor invasiveness, metastasis, angiogenesis, and drug resistance, supporting our findings for its role also in neovessel formation in the context of atherosclerotic plaque instability." (PMID 35494231, 2022). "In addition, ABCB5 expression was also associated with tumor progression and survival rate in cases of OSCC18." (PMID 26843453, 2016). "Furthermore, the ABCB5 levels were associated with advanced tumour stage and nodal metastasis." (PMID 32783366, 2020). "This study presents a unique contribution as the first comprehensive pan-cancer analysis of ABCA10 and ABCB5, highlighting their roles in tumor biology and clinical outcomes." (PMID 40445912, 2025). "Other genes such as ABCB5, CLDN5, RCC1 have also been implicated in CRC-related processes, with several studies suggesting their potential value in tumor diagnosis, progression monitoring, or prognostic evaluation." (PMID 40893943, 2025). "For TMZ specifically, the inhibition of ABCB1, ABCG2, ABCE1, ABCC1, and ABCB5 has seen significant decreases in either GBM tumor volume/weight by (~40–90% reduction), or significant increases in median survival (~1.3- to 5-fold increase)." (PMID 39861164, 2025). "The use of shRNAs, micro-RNAs, and monoclonal antibodies that directly inhibited ABCE1, ABCC1, and ABCB5 in vivo was followed by decreased tumor growth." (PMID 39861164, 2025). "The first in-depth pan-cancer analysis of ABCA10 and ABCB5 is presented in this study, offering valuable insights into their diverse roles in tumor biology." (PMID 40445912, 2025). "Using the median values of ABCA10 and ABCB5 gene expression, tumor cell lines were classified into groups with elevated and reduced expression levels, to obtain DEGs." (PMID 40445912, 2025). "ABCB5 is overexpressed in tumor stem cells and is correlated with chemoresistance and tumor recurrence." (PMID 40445912, 2025). "This multidimensional analysis reveals that ABCA10 and ABCB5 play distinct and opposing roles in tumor biology, providing valuable insights into their potential as prognostic biomarkers and therapeutic targets." (PMID 40445912, 2025). "Our analysis indicates that higher expression of ABCB5 is correlated with worse survival outcomes in tumor patients." (PMID 40445912, 2025). "These are percentages of deaths according to the variable age at diagnosis, gender, metastases, tumor site, ABCB5, WNT3A, and OPN markers, andp-values from statistical tests." (PMID 39239573, 2024). "We also show that key metastatic proteins (CSV and ABCB5) are co-expressed alongside nPKC-θ in CTCs and tumor metastases." (PMID 35326747, 2022).
tumor (continued). "Our results also found the risk score based on a 5-mRNA signature was significantly associated with tumor mutational burden (TMB) and tumor stem cell markers (CD20, CD38, ABCB5, CD44, etc.)." (PMID 34805163, 2021). "In OSCC, ABCB5 also has been considered as a putative CSC compartment and was associated with tumor progression." (PMID 32357409, 2020). "In conclusion, ABCB5 genetic variants had significant association with HCC risk and aggressive tumour properties." (PMID 32783366, 2020). "CSV, ALDH1A and ABCB5 are all key markers of metastatic breast cancer (MBC) circulating tumour cells (CTCs)." (PMID 29311580, 2018). "In the present work, BetA's anticancer activity against drug-resistant tumor cell lines was studied, in which either MDR-conferring ABC-transporters (P-glycoprotein, BCRP, and ABCB5) or mutation-activated EGFR were overexpressed." (PMID 29867487, 2018). "Differences in gene expression profiles of ABCB5, Lgr5, CD133, and CK20 dependent on the underlying tumor disease and thus on each T, and UICC stage was additionally compared between three different groups of patients." (PMID 34221246, 2017). "Expression of ABCB5 and Lgr5 in the bone marrow was dependent on tumor grading (both p=0.01) and T-category (p=0.036 and p=0.031, respectively)." (PMID 34221246, 2017). "In contrast to published reports, in which ABCB5 has been silenced on the day of tumor implantation, we began the treatment when the tumor was already palpable." (PMID 26910836, 2016). "In the present study, to gain some insight into the possible function of ABCB5 in tumor progression in OSSN, we performed immunofluorescence analysis that clearly revealed the elevated expressions of ABCB5 in all OSSN cases." (PMID 26843453, 2016). "Previous research also reported that blocking ABCB5 can inhibit tumor growth and reverse the resistance of CSCs to chemotherapeutic agents." (PMID 26910836, 2016). "We found this combined treatment of VNP20009 carrying shABCB5 with CTX efficiently reduced tumor growth and prolonged survival time by reducing ABCB5 expression and inhibiting chemotherapy resistance." (PMID 26910836, 2016). "This population displayed characteristics similar to those of CSCs and ABCB5 was identified to confer tumor growth and drug resistance in B16F10 cell line." (PMID 26910836, 2016). "Overexpression of ABCB5 and ASNS has been linked to resistance to doxorubicin in different tumor types." (PMID 25810463, 2015). "For example, the use of an antibody directed against ABCB5 prevented tumor formation or decreased tumor growth of a tumor already established." (PMID 24416617, 2013). "By comparing PAFC and FFC data, we estimated the percentage of ABCB5+ cells in circulation (up to 20%–40%) as compared to primary tumor cells (~5%), which suggests a more effective invasion rate of tumor-initiating cells in circulation." (PMID 24335964, 2013). "Using a monoclonal anti-ABCB5 antibody in nude mice, initial tumor growth as well as growth of established tumors was inhibited by antibody-dependent cell-mediated cytotoxicity in ABCB5+ cells." (PMID 20459772, 2010). "Furthermore, immunotherapy responses and immune infiltration across a variety of tumor types are associated with the expression levels of both ABCA10 and ABCB5." (PMID 40445912, 2025). "Mechanistic investigations revealed that ABCB5 promotes the ability of tumor cells to infiltrate into the blood vessels, which may be regulated by IL-8/AXL signaling." (PMID 40746888, 2025). "In addition, another study revealed that ABCB5 promotes tumor vascular invasion and metastasis by activating IL-8/AXL signaling." (PMID 40746888, 2025). "The distinct and opposing roles of ABCA10 and ABCB5 may reflect a complex interplay between tumor suppressive and oncogenic forces, necessitating further research to delineate their context-specific functions." (PMID 40445912, 2025).